CXCL8 (C-X-C motif chemokine ligand 8)
Diseases named in the same sentence as CXCL8 in open-access papers (continued):
Sharing a sentence is not in itself a finding about the gene and the disease.
tumor (continued). "The study demonstrated that high CXCL8 expression in the stromal compartment of the tumor, combined with increased numbers of CD68+ macrophages or elevated systemic neutrophil counts, was associated with poorer prognosis in CRC patients compared to healthy individuals." (PMID 40943634, 2025). "Several molecules such as CXCL8 were predicted target genes in tumor cells." (PMID 40510161, 2025). "However, macrophages aggregate in the adjacent area and it is the source of CXCL8 outside the tumor boundary." (PMID 39905539, 2025). "In CESC, CXCL8 fosters an immunosuppressive tumor microenvironment by recruiting neutrophils and regulatory T cells (Tregs), consistent with its correlation to advanced tumor stages and immune cell infiltration patterns." (PMID 40406253, 2025). "CXCL8, belonging to inflammatory chemokines, is expressed by various cell types and plays a key role in leukocyte trafficking during infections, inflammatory processes, tissue injury and tumor progression." (PMID 40124384, 2025). "Simultaneously, CXCL8 may participate in inflammatory responses and immune regulation through activation of the NF-κB pathway, further driving tumor progression by promoting the production of pro-inflammatory cytokines (Zhang JY." (PMID 40809844, 2025). "Additionally, the EP4 inhibitor suppresses pro-inflammatory cytokine IL-6, chemokine CXCL8, and inflammation-dependent bone metastasis, while alleviating immune suppression and restoring anti-tumor immunity." (PMID 40666730, 2025). "Beyond acute nucleic acid sensing, PARPi can induce treatment-related cellular senescence in tumor and stromal compartments, generating a senescence-associated secretory phenotype (SASP) enriched in IL6, IL8 or CXCL8, CCL2, GM-CSF, and members of the TGF beta family." (PMID 41488638, 2025). "Tumor-associated macrophages (TAMs), in particular, become pro-angiogenic, producing vascular-modulating enzymes like MMP9 and growth factors such as VEGF, CCL2, and CXCL8." (PMID 40647432, 2025). "In the C4 cluster, E4 cells showed increased expression of immune evasion genes such as CXCL8, which may help contribute to tumor growth by escaping from evade immune surveillance, enhancing immune resistance and angiogenesis ability." (PMID 40463392, 2025). "CXCL8, a potent chemokine, mediates neutrophil recruitment and tumor angiogenesis." (PMID 40299331, 2025). "CXCL8 exerts its action by triggering multidrug resistance genes like ABCB1 in tumor blood vessels, ABCB5 in mesothelioma, and ABCB 1 in gastric cancer and increasing the expression of NF-κB-regulated antiapoptotic genes like B-cell lymphoma 2 (Bcl-2) and inhibitor of apoptosis (IAP) families." (PMID 40076892, 2025). "Finally, in an in vivo mouse model, the researchers assessed CXCL8 expression and immune cell infiltration in the tumor microenvironment using immunohistochemistry and flow cytometry." (PMID 40573881, 2025). "This approach highlighted several putative iCAF-enriched populations from both normal and tumour samples; in normal tissues these included Stress-response Fib, CXCL8 + Breast Fib and universal (PI16+) fibroblasts; in tumours, IL11 + CAF, IGF1 + CAF and proto-CAF." (PMID 39757146, 2025). "In addition, YAP/TAZ controls the expression of pro-inflammatory interleukin-8 (IL-8/CXCL8) in tumor cells undergoing ER stress by a TRAIL-R2/DR5/caspase-8-dependent mechanism." (PMID 39904986, 2025). "The precise cellular origin of CXCL8 in the tumor microenvironment remains to be fully delineated, current evidence suggests that both tumor cells and infiltrating immune cells may contribute to its expression." (PMID 41432874, 2025). "IL-1β in the TME enhances CXCL8 secretion by tumor cells and the chemotaxis of M2 TAMs." (PMID 40607254, 2025). "The IL-8/CXCL8 autocrine signaling in tumor cells can induce the formation of NETs." (PMID 40165901, 2025). "In addition, it can accelerate tumor angiogenesis by regulating the NFkB C-X-C motif chemokine ligand 8 (CXCL8) axis." (PMID 38994952, 2024).
tumor (continued). "Furthermore, CXCL1 and CXCL8 expression in adenomatous polyps reached levels comparable to those observed in tumor tissues." (PMID 38979413, 2024). "Lactate-dependent induction of CXCL8 expression promoted tumor growth in vivo." (PMID 39706835, 2024). "Additionally, CXC motif chemokine ligand 8 (CXCL8) was included in the criteria, which is known for its critical role in tumor microenvironment (TME) alteration." (PMID 38698020, 2024). "Moreover, C-X-C-type chemokines including CXCL8 (IL-8), CXCL2, and CXCL12 secreted by CAFs are also involved in tumor proliferation by promoting angiogenesis and metastasis (CXCL8 & CXCL12) and increasing PD-L1 expression (CXCL2)." (PMID 38539448, 2024). "The role of CXCL8 in the tumor microenvironment (TME) is complex." (PMID 38694506, 2024). "Interestingly, within seven days, patients also experienced a significant drop in circulating tumor DNA and serum CXCL8, supporting the possibility of early anti-cancer effects occurring due to treatment." (PMID 38339310, 2024). "TA-pDCs recovered in ascites from ovarian tumor patients secreted the proangiogenetic factors CXCL8 and TNF-α, while in non-small cell lung cancer patients, tumor-infiltrating pDCs were reported to cause tumor proliferation via the pro-angiogenic effects of IL-1α." (PMID 38504978, 2024). "In addition, we found that EIF4G1 exerts a pro-inflammatory effect by modulating CXCL8 to affect the chemotaxis of macrophages toward tumor cells, a view supported by a previous report on CXCL8." (PMID 38405671, 2024). "Cytokines such as CXCL8, CXCL9, and CXCL10 are capable of attracting and activating immune cells, including macrophages and lymphocytes, causing their accumulation around the tumor." (PMID 38277205, 2024). "Furthermore, IL-6, CXCR4, CXCL8, and MMP-9 indicate higher diagnostic utility based on the AUC than the well-established tumor markers, such as CEA and SCC-Ag in OC patients." (PMID 38673838, 2024). "Recently, the chemokine CXCL8 has been discovered to play an important role in tumor progression." (PMID 38405671, 2024). "In this study, B7H4 was also shown to recruit tumour-infiltrating neutrophils through CXCL8." (PMID 39061159, 2024). "CXCL8 is mainly expressed in tumor cells as a marker gene for tumor healing." (PMID 38791369, 2024). "Literature has frequently reported the importance of CXCL8 for tumor angiogenesis." (PMID 38786066, 2024). "Furthermore, IL-6, CXCR4, CXCL8, and MMP-9 indicate higher diagnostic utility based on the area under the ROC curve (AUC) than well-established OC tumor markers, whereas CLDN18.2 can be used in novel targeted therapies for OC patients." (PMID 38673838, 2024). "Notably, the CXCL-8/CXCR-1 pathway was identified as a significant target, presenting a potential therapeutic strategy for addressing tumour-associated neutrophils." (PMID 38920685, 2024). "However, due to the higher expression of CXCR1 relative to CXCR2, CXCL8/IL-8 is more significant in this tumor’s development and function." (PMID 38673949, 2024). "In addition, CXCL8 is critical for activating and transporting inflammatory mediators and promoting tumor growth and metastasis." (PMID 38791369, 2024). "Furthermore, CXCL2, CXCL12, CCL2, and CXCL8 in humans have each been observed to regulate G-MDSC recruitment to the tumor microenvironment." (PMID 37988164, 2024). "On the other hand, eosinophils can secrete several pro-angiogenic factors, such as VEGF-A, fibroblast growth factor 2 (FGF-2) and CXCL8/IL-8, which may favor tumor progression." (PMID 39061080, 2024). "Remarkably, consistent with the great immunogenicity caused by the unstable genome profiles of the HRD group, HRD tumor epithelial cells exhibited high expression of immune chemokines that recruit immune cells to mediate antitumor effects, such as CXCL8, CXCL10 and CXCL11." (PMID 39136172, 2024).
tumor (continued). "Consequently, strategies aimed at modulating the activity of CXCL1, CXCL5, and CXCL8 hold promise as potential therapeutic interventions to impede tumor angiogenesis." (PMID 38047300, 2024). "Those include the up-regulation of antigen processing and presentation pathways in infected tumor cells and the up-regulation of proinflammatory cytokines IL1Β and CXCL8 in myeloid cells with bacteria engulfed, whose potential therapeutic relevance is discussed." (PMID 38959321, 2024). "Knockdown of CXCL8 inhibited angiogenesis and tumor growth and CXCL8 might serve as a potential new biomarker and therapeutic target to overcome epidermal growth factor (EGRF)-tyrosine kinase inhibitor (KI) resistance in the future." (PMID 38405671, 2024). "Furthermore, an obvious upregulation of CXCL8 secreted by tumor cell was also detected by immunohistochemistry in cirrhotic HCCs." (PMID 38388466, 2024). "In addition, studies have shown that the infiltration of TAMs in the TME leads to the increase of CXCL8 and enhances tumor invasion and angiogenesis." (PMID 36173487, 2023). "Previous studies also support the role of CXCL8 in tumour progression: CXCL8 enhanced tumour proliferation rate, angiogenesis and the ability to metastasize; recruited granulocytes at the site of inflammation; and high concentrations of CXCL8 were connected to worse survival in CRC patients." (PMID 37031328, 2023). "Therefore, the CXCL8/PLC pathway promotes tumor cell proliferation, migration, and invasion of normal tissues and angiogenesis, which makes cancer worsen and further develop." (PMID 37377954, 2023). "Therefore, emerging research suggests that combination therapies of monoclonal anti-CXCL8 antibodies or CXCR1/CXCR2 antagonists with standard anti-tumor (immuno)therapy can tackle the tumor immune escape and provide further benefit in anti-tumor treatment." (PMID 36725964, 2023). "While CXCL8/CXCR1 mainly increases tumor cell proliferation, CXCL8/CXCR2 enhances angiogenesis." (PMID 36614308, 2023). "In addition, CD271 activation reduces the levels of CXCL8, associated with cancer progression, thus also interfering with SCC-derived tumor spheroid invasiveness." (PMID 37443031, 2023). "The secretion of CXCL8 during CAF-induced SAT may therefore elicit tumor immune suppression through dynamic changes in the TME." (PMID 37174001, 2023). "In addition, CXCL8 can recruit neutrophils that affect several metastasis-specific processes in the tumor, such as migration, invasion, and angiogenesis, which is in line with our observation of increased neutrophils in the dnMBC group." (PMID 37686617, 2023). "Overexpression of CXCL8 in the tumor (microenvironment), by infiltrating immune cells, stromal cells, and the tumor cells themselves, promotes the migration of endothelial cells and formation of new blood vessels in the tumor." (PMID 36725964, 2023). "The function of CXCL genes, particularly CXCL8, in tumor development has been extensively studied." (PMID 37540227, 2023). "CXCL8 also plays a key role in recruiting neutrophils to the tumor microenvironment." (PMID 36725964, 2023). "Interleukin-8 (CXCL8, IL-8) is mainly produced by tumor cells themselves and via an autocrine loop, and paracrine signaling exerts pro-tumoral functions, so its serum concentration has been shown to correlate with tumor burden." (PMID 37849764, 2023). "C-C Motif Chemokine Ligand 2 (CCL2) or C-X-C Motif Chemokine Ligand 8 (CXCL8) could promote tumor proliferation and invasion in an autocrine and paracrine manner." (PMID 37895310, 2023). "Moreover, various SASP factors, including interleukins 1, 6 and 8, as well as chemokines CXCL8 and CCL2 have been associated with accelerated tumor proliferation and invasion in CRC." (PMID 38275386, 2023).
tumor (continued). "The endothelial junctions of tumor vessels are also aberrant and less cohesive: the glioblastoma secretome provides pro-angiogenic and inflammatory signals (here CXCL8), disrupts the junctions formed by VE-cadherin and promotes the permeability of brain endothelial cells." (PMID 37508458, 2023). "Since the secretion of CXCL1 and CXCL8 by cancer cells promoted TANs recruitment to the tumor sites, we hypothesized that ETV4 might promote TANs accumulation." (PMID 36670069, 2023). "Therefore, researchers can develop targeted drugs for tumor therapy based on the regulation of TAMs by CXCL8." (PMID 36173487, 2023). "HNSCC tumor cells produce IL-6, CXCL8, and epidermal growth factor (EGF), which improve the survival and angiogenic potential of endothelial cells through the activation of the STAT3/protein kinase B (AKT)/extracellular signal-regulated kinase (ERK) signaling pathways." (PMID 38003931, 2023). "However, LPS treatment also increased CXCL8, coding for IL8, a known pro-angiogenic factor in the tumor microenvironment, where neovascularization is one of the main characteristics of GBM responsible for its aggressiveness." (PMID 36765551, 2023). "The present in vitro findings suggest that the GPM-GBM subtype with activated inflammatory TLR4 pathway may respond to MET treatment and that combination treatment with CXCL8/IL8-inhibitor may improve tumor growth control." (PMID 36765551, 2023). "Neoplastic cells are able to produce and release CXCL8, which in turn acts on the tumor microenvironment, promoting angiogenesis, epithelial–mesenchymal transition, increased endothelial cell permeability, suppressing anti-tumor immunity, and eventually favoring clone motility and invasiveness." (PMID 37760903, 2023). "The angiogenic and inflammatory effect of CXCL8 promotes uncontrolled tumor growth and metastasis." (PMID 36725964, 2023). "Moreover, tumor-secreted cytokines like CXCL8, PDGF, MIP1 and CSF3 increase the mobilization of neutrophils from the bone marrow and spleen, leading to an elevated neutrophil-to-lymphocyte ratio in both human and mouse studies." (PMID 37566060, 2023). "Inhibition of CXCL8 could be considered a therapeutic target, and the tumour necrosis percentage could be evaluated as a potential predictive biomarker." (PMID 37031328, 2023). "CXCL8, a proinflammatory chemokine, showed significant positive correlation with tumour necrosis." (PMID 37031328, 2023). "Based on our latest results, we concluded that serum CXCL-8 might be a better biochemical marker candidate in the diagnosis of CRC than the classical tumor marker (CEA)." (PMID 37509572, 2023). "In addition, we proved the role of CXCL8 as a potential GC biomarker, especially in combined measurement with classical tumor markers." (PMID 37240178, 2023). "High expression of CXCL8 by tumors has been correlated with poor prognosis in many tumor types." (PMID 37114134, 2023). "CXCL8, secreted by macrophages and epithelial cells, is an active angiogenic factor and proinflammatory factor, taking part in the cancer development, including change of tumor microenvironment, tumor migration, tumor proliferation and so on." (PMID 37393391, 2023). "Testing in either cell culture or the tumor xenografts showed that ACKR1 expression could prevent the spike of CCL2 and CXCL8 released into the growth media or tumor microenvironment." (PMID 37006247, 2023). "The Mac_CXCL8 subgroup showed a somewhat suppressed phenotype in most macrophage-related functions except for angiogenesis, this group was also the least active in cell–cell interactions, suggesting a dormant and potentially pro-tumor role in the TME." (PMID 37287069, 2023). "Moreover, CXCL8 recruits myeloid-derived suppressor cells (MDSCs) to TME, which enhances the motility of tumor cells, endothelial cells, or tumor-associated leukocytes and promotes the immune evasion of tumor cells." (PMID 37377954, 2023).
tumor (continued). "CXCL8 promotes tumor progression at multiple levels: by directly potentiating the migration and survival of cancer stem cells, by acting on endothelial cells to stimulate angiogenesis, and by inducing the trafficking of neutrophils and MDCSs which can thereby locally restrain anti-tumor immunity." (PMID 37444436, 2023). "Thus, the combination of targeting CXCL8 and blocking the PD-1 pathway synergistically increased the tumor immune response and inhibited tumor progression." (PMID 37898619, 2023). "For instance, CXCL8 favors tumor angiogenesis by stimulating the survival of endothelial cells." (PMID 36980182, 2023). "To further probe a direct link between cancer cell–intrinsic HERVH-CALB1 and CXCL8 expression, we examined RNA-Seq data from in vitro–grown lung squamous and adenosquamous cancer cell lines, where the confounding effects of tumor heterogeneity or purity can be excluded." (PMID 37192000, 2023). "Moreover, several chemokines have been reported to have immunosuppressive activity under tumor conditions, where CXCL8 is an example of these chemokines." (PMID 37175004, 2023). "CXCL8 is also known for its ability to induce epithelial-to-mesenchymal transition of tumor cells." (PMID 36725964, 2023). "Additionally, the median CXCL8 (IL8) gene expression in normal tissue was 177 (Q1: 70, Q3: 469) compared to 3407 (Q1: 1399, Q3: 7577) in tumour tissue and 2070 (Q1: 910.5, Q3: 3912.5) in metastatic tissue (p= 3.48 × 10−132, Kruskal–Wallis test)." (PMID 36835258, 2023). "Finally, although most of the studies point out a pro-tumorigenic role for CXCL8, there are some reports describing a beneficial role of CXCL8 in the anti-tumor (immune) response in similar cancers, probably mainly induced through leukocyte recruitment." (PMID 36725964, 2023). "Here, we demonstrate that the ability of PD-L1 to induce cell-autonomous- and PD-1-induced effects is mediated through STAT3 and STAT1 activation, leading to increased tumor cell growth, CXCL8 release and cancer cell invasion in luminal A and TNBC breast cancer cells." (PMID 37830552, 2023). "Whereas these vesicles triggered IL-6 and CXCL8 expression, further studies will be required to clarify how such induction may impact tumor progression." (PMID 37833751, 2023). "Together, our findings connect Y705-STAT3 activation to the negative regulation of intrinsic HR+/HER2− pro-metastatic properties (CSC, EMT-like) and positive control of functions that can affect the inflammatory/immune milieu at the tumor site (CXCL8, PD-L1 expression)." (PMID 37190183, 2023). "It has been shown that CD58/CD2 interaction stimulated the synergistic secretion of CXC chemokine ligand 8 (CXCL-8/IL-8) of human intestinal CD3 + TCRαβ + CD8+ intraepithelial lymphocytes (IELs), and CXCL-8 induces cell proliferation and migration, promoting tumor cell growth in CRC." (PMID 37836662, 2023). "Mechanistically, overexpression of MIF in NSCLC increases the phosphorylation level of JNK, c-Jun, and subsequent activity of the transcription factor AP-1 in a CD74-dependent manner, which promotes tumor angiogenesis by increasing expression of the angiogenic factors CXCL8 and VEGF." (PMID 35842634, 2022). "Expression of CXCL8 mRNA within each TME compartment (tumour epithelium/tumour‐associated stroma) was assessed for association with clinical characteristics including survival outcomes and tumour histology." (PMID 35879507, 2022). "Given that tumor-associated macrophages (TAMs) can mediate cancer metastasis, chemotherapeutic resistance, and immune evasion through secreting CD24, CXCL8, CCL2, and other cytokines, SLC1A5 is probably involved in the formation of the immune-tolerant microenvironment." (PMID 35419359, 2022). "Taken together, these results indicate that serum concentrations of CXCL-8 may represent an improved novel biochemical marker for CRC diagnostics compared to clinical practice tumor markers." (PMID 36567905, 2022).